RAD51C (RAD51 paralog C)
Diseases named in the same sentence as RAD51C in open-access papers (continued):
Sharing a sentence is not in itself a finding about the gene and the disease.
tumor (continued). "72% of patients had BRCA-wildtype tumours and 1 patient (6%) had a RAD51C mutation." (PMID 36348385, 2022). "for deleterious ERCC4 variants, the effectiveness of cisplatin is expected for disrupting mutations; PARP inhibitors are selectively toxic to tumours with RAD51C mutations, and tumours with ATM mutations had a positive response to cisplatin, and inhibitors of PARP1, ATR and DNA-PKc." (PMID 32756499, 2020). "In the ARIEL2 and ARIEL3 clinical trials, although BRCA mutations or genomic LOH was associated with better tumor response than BRCA1 or RAD51C methylation, copy number profile or mutations in other relevant genes, the outcome with rucaparib was generally better than that obtained with placebo." (PMID 30518089, 2018). "With the exception of OV and TNBC, RAD51C methylation was also generally detected at a low tumour level (<70%, suggestive of heterozygous or subclonal status) and without accompanying LOH or HRD scarring." (PMID 39055334, 2024). "Follow-up studies examining the frequency of low tumour BRCA1 or RAD51C methylation in the chemo-naïve setting will be critical for understanding early treatment resistance in OV and BC." (PMID 39055334, 2024). "Despite having a significant impact on tumor proliferation, there is robust binding of the G264S variant to XRCC3 slightly exceeding that of wild-type RAD51C." (PMID 37488098, 2023). "The proportion of variants that were present on both tumor and germline testing varied widely by gene, with the highest proportion found in CHEK2 variants (85.7%, N = 6) and the lowest proportion found in RAD51C variants (0%, N = 0)." (PMID 35962742, 2023). "In a study of patients with tumor CGP-identified mutations in moderate risk breast and ovarian CSGs (ATM, BRIP1, CHEK2, PALB2, RAD51C, and RAD51D), 24% of patients with germline variants would not have met criteria for germline testing." (PMID 37568048, 2023). "The extent of LOH in chromosome 17q varied across tumours with high HRD scores, with many showing hemizygous loss across BRCA1, RAD51C and RAD51D." (PMID 35039523, 2022). "From the 52 tumor samples, variant analysis, large rearrangement analysis of HRR genes and assessment of promoter methylation of BRCA1 and RAD51C were performed on 52, 50 and 47 samples, respectively." (PMID 36294734, 2022). "Given these limitations of case–control analyses, insights from tumour sequencing, including identifying a “second hit” and characteristic genome alterations, may offer the best avenue for validating or refuting a role for RAD51C MS variants in BC predisposition." (PMID 35039523, 2022). "The frequency of rare RAD51C MS variants was assessed in the BEACCON study of 5734 familial BC cases and 14,382 population controls, and findings were integrated with tumour sequencing data from 21 cases carrying a candidate variant." (PMID 35039523, 2022). "In our cohort, a comprehensive tumor profile including homologous recombination genes (i.e., ATM, PALB2, RAD50, RAD51, RAD51B, RAD51C, RAD51D...) was performed for 100 cases, finding pathogenic alterations in four tumor samples, as previously reported." (PMID 35406410, 2022). "Overall, 28% of carriers of HR-related gene variants had a presence of HR-deficiency associated tumor mutational signature, which increased to 86% of carriers when only well-recognized HR genes (BRCA1, PALB2 and RAD51C) were included." (PMID 33917078, 2021). "LOH or AST mutation was detected in at least one tumor with PALB2, ATM, RAD51D, BARD1, BRIP1, RAD51C, or NF1 germline mutation." (PMID 32566746, 2020). "It is not uncommon for tumor-suppressing factors to rely on a secondary mutation to initiate tumor development, and in fact, this trend is also observed in BRCA1, BRCA2, and RAD51C mutations." (PMID 31775907, 2019).
tumor (continued). "Significant, tumour-specific loss of heterozygosity occurs in nine genes (ATM, BAP1, BRCA1/2, BRIP1, FANCM, PALB2 and RAD51C/D)." (PMID 26689913, 2015). "To identify novel tumor-specific promoters, we examined expression levels of Rad51 paralogs, Rad51B, Rad51C, and Rad51D as well as Rad52 in a panel of normal and tumor cell lines." (PMID 24742710, 2014). "Given the complexity of HRD biomarkers, key assay features include the selection of HRR genes (BRCA1, BRCA2, PALB2, RAD51C, RAD51D), definitions of genomic scars (LOH, TAI, LST), mutational signatures analyzed, use of comparator samples, and tumor-specific HRD score calculations." (PMID 40864792, 2025). "BRCA2 mutations occur in 5–10% of prostate cases, and RAD51C/RAD51D, BRIP1, or BARD1 defects may broaden eligibility across tumor types." (PMID 40864792, 2025). "Furthermore, genetic inactivation of POLQ is synthetic lethal with HR defects caused by either BRCA1, BRCA2, ATM, RAD51C or FANCD2 defects and tumour overexpression of POLQ correlates with HRD status and a poor clinical outcome." (PMID 35567571, 2022). "Unfortunately, the minimal amount of RAD51C expression required to confer tumor-suppressor haplosufficiency is unknown, and so these splicing assays were not considered informative (PVS1_O_N/A)." (PMID 35740625, 2022). "Here, we review the molecular features and hereditary tumor risk associated with several moderate-penetrance genes in EOC that are involved in the homologous recombination repair pathway, i.e., ATM, BRIP1, NBN, PALB2, and RAD51C/D." (PMID 36233090, 2022). "In 85% of patients, tumours harboured a BRCA mutation, and 1 patient (3%) had a RAD51C mutation." (PMID 36348385, 2022). "Although the mechanisms of aberrant RAD51C and RAD51D in conferring risk to OC is unknown, our LOH analyses of tumour DNA from carriers are consistent with independent studies that have demonstrated loss of the protein function in tumour cells." (PMID 35565380, 2022). "Among BRCA1/2 wild-type tumors, both BRIP1-mutated tumors were Sig3 positive while the RAD51C deleted tumor was Sig3 negative." (PMID 34552099, 2021). "As BRCA1 or RAD51C gene silencing through promoter methylation has been detected in ovarian and breast tumours and has been associated with HRD cases, a potential mechanism of resistance to PARPi in these tumours would involve gene re-expression." (PMID 35008208, 2021). "Nine cases with germline variants in HR-related genes PALB2, BRCA1, RAD51C, FAN1 and CHEK2 also showed evidence of enrichment of the germline variant in the tumor, while the other 12 cases with HR-related gene variants (seven FAN1, three CHEK2, one BRIP1, one NBN) did not." (PMID 33917078, 2021). "RAD51C is another major player of the pathway, and has been identified as a susceptibility loci for TGCT formation, again supporting the relevance of the HR pathway in this tumor model." (PMID 33513287, 2021). "Reversions have not only been detected in tumours with BRCAm but also in tumours with mutations in other HRR genes such as PALB2, RAD51C and RAD51D, which reinforces the notion that mutations outside of BRCA genes that impact HRR are valid selection biomarkers for PARPi therapy." (PMID 35008208, 2021). "We observed genetic heterogeneity also in spheroids for several genes, as indicated by low SNV frequencies, for instance, in ADAMTS7, CSMD3, ERN1, FAT3, and RAD51C/D, supporting the view that tumor lesions are composed of mixed tumor cell populations with varying frequencies of SNVs." (PMID 32533757, 2020). "However, the mean RAD51C methylation, observed in the patient’s tumor (0.13), was lower than that observed in blood and within the normal range with respect to normal breast tissues (0.11–0.16)." (PMID 30634417, 2019).
tumor (continued). "It is noticeable that RAD51C has been proved to be a tumor suppressor." (PMID 29207658, 2017). "Our results indicated that germline truncation and missense variants in several genes were under selection in the tumour, with ATM, BRCA1, BRCA2 and RAD51C determined as significant from both truncation and missense analyses and BAP1, BRIP1, FANCM, PALB2 and RAD51D from truncation analysis alone." (PMID 26689913, 2015). "Pathogenic RAD51C variants contribute to breast cancer risk, and elevated RAD51 levels in cell lines and primary tumors suggest that driving the HR pathway beyond physiological levels may also play a role in genomic instability and hence tumor progression." (PMID 39334297, 2024). "In contrast, monogenic BRCA2 or RAD51C tumor mutations confer only a minor but insignificant decrease in overall survival compared to patients with no BRCA2 or RAD51C mutation, revealing genetic vulnerability associated with the polygenic BRCA2 + RAD51C mutations." (PMID 36906610, 2023). "BRCA1 methylated tumours are also sensitive to PARP inhibition, as are tumours with mutations in other genes that function in repair of double strand breaks (DSBs), including RAD51C, RAD51D, ATM and PALB2, where tumours are described as having a “BRCAness” phenotype." (PMID 34445211, 2021). "The specific HRR mutations identified in the 21 tumour samples were: BRIP1 (n = 5), CDK12 (n = 3), RAD54L (n = 2), RAD51B (n = 2), RAD54L rearr (n = 1), ATM rearr (n = 1), FANCA rearr (n = 1), FANCD2 (n = 1), FANCL rearr (n = 1), FANCL (n = 1), RAD51C (n = 1), RAD52 del (n = 1), XRCC3 rearr (n = 1)." (PMID 30353044, 2018). "The identified epigenetic PARPi hallmarks contained hundreds of DMRs; however, only a few DMRs were reported as tumor driver genes (SOX2, POU2AF1, PTK6, VHL, JAK3, and EZH2) or as HRD genes (RAD51C)." (PMID 38927686, 2024). "RAD51 paralogs, including RAD51B, RAD51C, RAD51D, XRCC2 and XRCC3, have emerged as essential tumour suppressors, forming two subcomplexes, BCDX2 and CX3." (PMID 39268578, 2024). "The complexity of the tumour methylation level analysis, which is reliant on accurate tumour purity and copy number estimation, is a known limitation of BRCA1 and RAD51C methylation characterisation studies." (PMID 39055334, 2024). "We observed a significant association between OS and the expression of six genes (CCNH, MLH3, RAD51C, RPA3, SLK, and XPA) in primary tumor tissues." (PMID 37240218, 2023). "Four of these patients (11.8%) carried a possible germline PV/LPV detected in the BRCA1, RAD51C, BRIP1, or PTEN gene in the tumor sample." (PMID 35326583, 2022). "Since we have detected potentially actionable PV/LPV for PARP inhibitor therapy in BRIP1 and RAD51C genes, the final percentage of actionable detected PV/LPV with germline genotyping was 66.6% (28/42), and with tumor genotyping 97.6% (41/42)." (PMID 35326583, 2022). "Here, we examined the impact of tumor-specific thresholds and measurement of promoter methylation of BRCA1 and RAD51C on unexplained proportions of HRD cases across various tumor types." (PMID 35783256, 2022). "In our study, we tested tumor DNA by NGS with a small HR-gene panel, as well as BRCA1 and RAD51C promoter methylation." (PMID 36294734, 2022). "Tumor analysis highlighted germline variation in HR-related repair genes, particularly BRCA1, PALB2 and RAD51C, to have a potential driver role in EC development based on the presence of mutational signature indicative of HR deficiency." (PMID 33917078, 2021). "Deleterious alterations in DDR genes associated with increased sensitivity to PARP inhibitors in other tumor types (e.g. BRCA1, BRCA2, PALB2, RAD51C and RAD51D) were infrequent (9.4%) in ATLAS." (PMID 34030643, 2021). "In germline BRCA1/BRCA2/RAD51C/RAD51D/BRIP1 PVs, 44.4% (24/54) had a positive FH compared to 11.3% (28/249) of sporadic tumours (p < 0.001)." (PMID 34503154, 2021).
tumor (continued). "The effect of RAD51C silencing on PARP inhibitor treatment in cancer cell lines and xenografts was also investigated, and was found to significantly sensitize tumours to treatment and inhibit tumour growth." (PMID 36046263, 2020). "Five HR cofactors – the RAD51 paralogs RAD51B, RAD51C, RAD51D, XRCC2 and XRCC3 – recently emerged as crucial tumor suppressors." (PMID 32669601, 2020). "Our group and others have successfully identified tumor-specific promoters of two HR factors, RAD51 and RAD51C, which can be used for transcriptionally targeting tumor cells in vitro and in vivo." (PMID 29549248, 2018). "Our investigation aims to unravel potential associations with other non-BC or non-OC tumour types with pathogenic or likely pathogenic mutations (hereinafter, PVs) in the RAD50, RAD51C, RAD51D, and BRIP1 genes." (PMID 40282418, 2025). "Remarkably, pathogenic variants in BRCA1/2 were present in patients both with and without clinical benefit, whereas variants in other known homologous recombination repair (HRR) genes were identified exclusively in tumor samples from patients with clinical benefit (ABRAXAS1, FANCA, and RAD51C)." (PMID 39591206, 2024). "We also observed no LOH in some of the tumour DNA from OC carriers of our RAD51C c.705G>T; p.Lys235AsnAs and RAD51D c.620C>T; p.Ser207Leu, as the DNA was extracted post-chemotherapy treatment, suggesting the possibility of stromal cell contamination." (PMID 36969007, 2023). "Similarly, alterations in DNA damage response genes such as ATM, CDK12, and those of the RAD family (RAD51C, RAD54L) were observed across multiple tumour types." (PMID 37120671, 2023). "Apart from RAD51C, none of the high HRD tumours harboured biallelic loss of other known HRD drivers, such as BRCA1 or BRCA2." (PMID 35039523, 2022). "For example, in the PROfound trial, 145 patients with a tumor BRCA2 alteration were randomized while no patients with a tumor FANCL or RAD51C alteration were randomized." (PMID 35768576, 2022). "If PV/LPV in RAD51C and BRIP1 genes, besides BRCA genes, are also considered as potentially actionable for treatment with PARP inhibitors, then a total of 42 potentially actionable PV/LPV were detected by tumor or germline genotyping." (PMID 35326583, 2022). "As recently reported, an NGS profiling including HR genes (BARD1, BRIP1, PALB2, RAD51C, and RAD51D) could improve the rate of tumor with HRD by 5–6%, identifying patients who may mostly benefit from PARPi therapy." (PMID 35406410, 2022). "Although defects in other key HRR proteins such as PALB2 account for some of these HRD-positive tumours, it is also important to highlight that some HRR genes, in particular BRCA1 and RAD51C, show high levels of promoter hypermethylation leading to gene silencing in breast and ovarian cancer." (PMID 35008208, 2021). "In addition, reversion mutations leading to regained function of HR-proteins (e.g., BRCA1, RAD51C and RAD51D) in tumor cells result in PARP resistance." (PMID 30441849, 2018). "The somatic NAHR burden did not vary by tumor type nor was it lower in tumors harboring biallelic pathogenic mutations in DNA repair genes, including frequently mutated homologous recombination pathway mediators (BRCA1, BRCA2, PALB2 and RAD51C)." (PMID 37945902, 2023). "Finally, one patient with FH(−) and with BC as the only tumor (diagnosed at 26 years of age) was found to have a non-coding spliceogenic LPV in RAD51C (c.965 + 5G > A)." (PMID 36329109, 2022). "Therefore, downregulation of these DDR genes e.g., RAD51C, LIG1 and POLD1-3 may produce synergies towards formation of persistent unrepairable complex DSB in tumor cells treated with dual combination leading to cell growth arrest and lethality." (PMID 30042828, 2018). "This is exemplified by PARPi used to treat breast, prostate, pancreatic or ovarian cancers with defects in the HR pathway, controlled by the tumour suppressors including (but not exclusive to) BRCA1, BRCA2, PALB2, RAD51C and RAD51D." (PMID 35567571, 2022).
tumor (continued). "However, to date, there is a lack of comprehensive data describing other tumor characteristics such as histological subtype and tumor size and stage in PALB2, RAD51C, and RAD51D GPV carriers." (PMID 40428378, 2025). "In primary tumor tissue, the string correlations among CCNH, XPA, and SLK are interesting: CCNH and its correlation with CDK7 and, last but not least, the correlation of CDK7 in strings with RAD51C and XPA." (PMID 37240218, 2023).
RAD51C also shares sentences with these, for which no sentence is quoted: breast (4 papers); hereditary breast and ovarian cancer syndrome (4); Hereditary Ovarian Cancer (3); acute promyelocytic leukemia (2); genetic disorder (2); head and neck cancer (2); Hereditary Cancer Syndromes (2); melanoma (2); mucositis (2); neuroblastoma (2); pancreatic adenocarcinoma (2); adenocarcinoma (1); Alzheimer disease (1); Autoimmunity (1); autosomal recessive disease (1); B-cell lymphomas (1); basal cell carcinoma (1); benign tumors (1); bladder cancer (1); brain tumors (1); cervix cancer (1); chronic myeloid leukemia (1); clear cell carcinoma (1); cryptorchidism (1); dermatitis (1); Desmoid-Type Fibromatosis (1); embryonal rhabdomyosarcoma (1); endometrioid carcinoma (1); epithelial ovarian tumors (1); esophageal cancer (1).
A further 38 diseases each share a sentence with RAD51C in 1 paper.